VEGFA (vascular endothelial growth factor A)
Diseases named in the same sentence as VEGFA in open-access papers (continued):
Sharing a sentence is not in itself a finding about the gene and the disease.
diabetic macular edema (434 papers, 2007 to 2026). "Vascular endothelial growth factor-A (VEGF-A) plays an important role in the development of diabetic macular edema (DME)." (PMID 40821158, 2025). "OCTA imaging is fast and thus useful for patients that require recurrent vascular imaging, such as those being treated with vascular endothelial growth factor antagonists (anti-VEGF) for wet AMD or diabetic macular edema (DME)." (PMID 33292740, 2020). "In patients with diabetic macular edema (DME) from YOSEMITE/RHINE, dual angiopoietin-2/vascular endothelial growth factor-A (VEGF-A) inhibition with faricimab resulted in visual/anatomic improvements with extended dosing." (PMID 39388397, 2024). "Previous basic studies clearly revealed that vascular endothelial growth factor-A (VEGF-A) and angiopoietin 2 (ANG2) are major players in the pathogenesis of diabetic macular edema (DME)." (PMID 37109622, 2023). "Restoration of the barrier function via inhibition of vascular endothelial growth factor-A (VEGF), a potent inducer of angiogenesis and vascular permeability, is currently an effective treatment for diabetic macular edema (DME) and a promising treatment option for vasogenic brain edema." (PMID 30231925, 2018).
pancreatic cancer (422 papers, 1999 to 2026). "The prognostic risk score model contained three genes: GSK3B, IL18 and VEGFA, all of which were highly expressed in pancreatic cancer tissue and were associated with poor prognosis." (PMID 36743929, 2022). "We applied Cox and LASSO regression analysis to develop a neuroendocrine regulation- and metabolism-related prognostic risk score model with three genes (GSK3B, IL18 and VEGFA) for pancreatic cancer." (PMID 36743929, 2022). "Our study discovered that high expression of VEGFA was linked to the poor prognosis for pancreatic cancer." (PMID 36743929, 2022). "MYOF is implicated in the regulation of vascular endothelial growth factor A (VEGFA) secretion and has an impact on tumor-associated angiogenesis in human pancreatic cancer." (PMID 34957301, 2021). "As the most specific and major angiogenic factor, VEGFA overexpression was suggested as a diagnostic and prognostic factor for pancreatic cancer." (PMID 35201478, 2021). "For example, previous study has reported that VEGFA/76336/ES significantly associated poor survival in pancreatic cancer." (PMID 32095320, 2020). "Investigations into such information reflected that VEGFA was closely associated with tumor angiogenesis in pancreatic cancer tissues." (PMID 27015364, 2016). "Based on data that has attributed cellular functions to fibroblast proliferation in other tissues, we investigated a panel of ten central regulators of cell proliferation (c-Myc, Cyclin D1, Cyclin E1, FGF2, FGFR2, EGFR, EGF, FGF1, FGFR1 and VEGFA) in pancreatic cancer-associated fibroblasts (CAFs)." (PMID 38678032, 2024). "However, VEGFA/76336/ES significantly associated unfavorable prognosis, which indicating its multifaceted roles in pancreatic cancer progression." (PMID 31552163, 2019). "However, VEGFA/76336/ES significantly associated poor survival in pancreatic cancer, which is inconsistent with previous data." (PMID 31552163, 2019). "Our findings indicate that CXCL10 potentially facilitates the progression of pancreatic cancer by modulating the expression of vascular endothelial growth factor A (VEGFA), thereby inducing macrophage polarization towards the M2 phenotype." (PMID 40129528, 2025). "Pancreatic cancer overexpresses proangiogenic proteins such as vascular endothelial growth factor A (VEGFA), contributing to treatment resistance." (PMID 41294859, 2025). "ZNFTR interacts with ATF3 to sequester ATF3 away from the ZNF24 promoter, increase ZNF24 expression, and downregulate VEGFA transcription, thereby reducing the proliferative, metastatic, and proangiogenic abilities of pancreatic cancer cells." (PMID 39790557, 2025). "Under hypoxic conditions, downregulation of ZNFTR expression decreases ZNF24 expression via ATF3, resulting in the upregulation of VEGFA, which promotes pancreatic cancer progression." (PMID 39790557, 2025). "For example, lncRNA-ZNFTR inhibits pancreatic cancer cells by regulating the ATF3/ZNF24/VEGFA pathway." (PMID 35647035, 2022). "VEGFA-VEGFR2 is known to increase the motility of pancreatic cancer cells and induce invasion, migration, and metastasis." (PMID 35052825, 2022). "The combined inhibition of FGF2 and VEGFA was highly efficient in preclinical models of head and neck carcinoma or pancreatic tumors." (PMID 32775327, 2020). "Vascular endothelial growth factor-A (VEGF-A) in pancreas cancer cells increases cell motility and decreases ZO-2 expression." (PMID 31450555, 2019). "VEGFA mediated inhibition of several cytokines in the cultured pancreatic cancer cell line is discussed in details." (PMID 29511477, 2017). "In conclusion, our results suggested that the Twist/miR-497/VEGFA axis is significantly correlated with metastasis and angiogenesis in pancreatic cancer." (PMID 27015364, 2016). "A positive correlation between Twist and VEGFA levels in pancreatic cancer specimens was observed in this study." (PMID 27015364, 2016).
pancreatic cancer (continued). "In this study, we showed for the first time that Twist played an important role as a promoter of angiogenesis in human pancreatic cancer through regulation of miR-497/VEGFA axis." (PMID 27015364, 2016). "In this study, for further investigate the interrelationship between Twist, miR-497 and VEGFA in pancreatic cancer, we examined the effect of Twist/miR-497/VEGFA axis in metastasis and angiogenesis in pancreatic cancer cells both in vitro and in vivo." (PMID 27015364, 2016). "In comparison with normal tissues, the levels of miR-497 and VEGFA mRNA were down-regulated and up-regulated in pancreatic cancer tissues, respectively." (PMID 27015364, 2016). "Our results conclusively demonstrated that the angiogenic effect of Twist is correlated by VEGFA in pancreatic cancer angiogenesis." (PMID 27015364, 2016). "The expression levels of miR-497 and VEGFA in 68 cases of pancreatic cancer specimens as well as their matched adjacent normal pancreatic tissues were analyzed by qRT-PCR." (PMID 27015364, 2016). "By analyzing the expression levels of miR-497, Twist was found inversely correlated with miR-497 in pancreatic cancer tissues, and a positive correlation was found between Twist and VEGFA levels in pancreatic cancer specimens." (PMID 27015364, 2016). "Interestingly, myoferlin is also required for angiogenic cascades by maintaining VEGFR2 and TEK expression in endothelial cells, and VEGFA secretion in pancreatic cancer cells." (PMID 35205843, 2022). "VEGF family members, especially VEGFA, have been found to play important role in pancreatic cancer." (PMID 35201478, 2021). "In conclusion, our current findings are consistent with the hypothesis that Twist promotes angiogenesis via miR-497/VEGFA axis in pancreatic cancer." (PMID 27015364, 2016). "The hypothesis derived was that Twist-induced angiogenesis in pancreatic cancer was correlated by VEGFA." (PMID 27015364, 2016). "To investigate whether VEGFA contributed to Twist-induced angiogenesis in pancreatic cancer, we successfully acquired VEGFA-overexpressed Bxpc-3 and VEGFA-depleted Capan-1 cells." (PMID 27015364, 2016). "Consequently, we hypothesize that CXCL10 may facilitate the progression of pancreatic cancer by inducing macrophage polarization towards the M2 phenotype through the upregulation of VEGFA." (PMID 40129528, 2025). "However, the precise mechanisms by which CXCL10 regulates VEGFA expression in pancreatic cancer remain unclear, necessitating further investigation in subsequent studies." (PMID 40129528, 2025). "In addition, the lncRNA zinc finger protein 24 transcription regulator (ZNFTR) plays an inhibitory role in pancreatic cancer (PC) by modulating the activating transcription factor (ATF3)/zinc finger protein 24 (ZNF24)/vascular endothelial growth factor A (VEGFA) pathway." (PMID 36544907, 2022). "Nonetheless, how VEGFA related to angiogenesis in pancreatic cancer remains unknown." (PMID 27015364, 2016). "The impact of MMP28 on pancreatic cancer growth and TAMs was partially reversed by inhibiting either the JNK signaling pathway or the effects of IL-8 and VEGFA." (PMID 39972459, 2025). "Briefly, MMP28, which is overexpressed in pancreatic cancer, mediates the recruitment of TAMs through phosphorylation of the MAPK/JNK signaling pathway, stimulating the secretion of IL-8 and VEGFA by cancer cells." (PMID 39972459, 2025). "With demonstrated involvement in the VEGFA/PI3K/AKT pathway, miR‐4739 has been reported to play an antioncogenic role in pancreatic cancer." (PMID 39587714, 2024). "In pancreatic cancer, METTL3 increases the stability of lncLIFR-AS1 and indirectly promotes VEGFA expression." (PMID 39098905, 2024). "TK1258 also known as Dovitinib which inhibits multiple kinases also impairs the FGF1, FGF2, VEGFA, and PDGFB in Pancreatic cancer cells." (PMID 38474109, 2024).
pancreatic cancer (continued). "By analysing the TCGA database, we found that the expression of PCDH1 was positively correlated with CCND1, CCNE2, VEGFA, MET, CD44 and CD133 expression in pancreatic cancer tissues." (PMID 35864095, 2022). "In pancreatic cancer, FXR downregulation resulted in decreased VEGFA mRNA transcription through impaired DNA-binding activity of NF-κB." (PMID 35681743, 2022). "Curcumin suppresses pancreatic tumor development by raising the expression of CELF2, which prevents COX-2 and VEGFA (Vascular Endothelial Growth Factor A) mRNAs from being translated." (PMID 34681716, 2021). "Bevacizumab is an mAb that is specific for vascular endothelial growth factor A (VEGF-A) and has been labeled with IRDye800 for in vivo optical imaging to guide surgical resection of breast and pancreatic cancer." (PMID 30224903, 2018). "Similar to other pro-angiogenic factors like VEGFA and PlGF secreted by tumor cells, ADM promotes pancreatic cancer growth through stimulating tumor angiogenesis and recruiting myelomonocytic cells." (PMID 27391260, 2016). "For example, STAT3 signaling plays a direct role in the regulation of vascular endothelial growth factor-A (VEGF-A) expression, and its activation is essential for VEGF-A overexpression in pancreatic cancer, a key regulator in abnormal tumor angiogenesis." (PMID 23923060, 2013). "Consequently, targeting IL-8 and VEGFA production and secretion has emerged as a promising strategy for TAM-based pancreatic cancer treatment." (PMID 39972459, 2025). "This promoting effect of METTL3 on VEGFA is also observed in CRC, pancreatic cancer and BLCA." (PMID 39098905, 2024). "Similar to this, E2F7 exerts an actively transcriptional effect, but not repressively as general, was found in pancreatic cancer, and promotes tumor cell proliferation by efficient enhancement of VEGFa transcription." (PMID 35924788, 2022). "Breast or pancreatic cancers for example rely on these angiogenic factors rather than on VEGFA and are poor responders to bevacizumab." (PMID 32775327, 2020). "Moreover, the VEGFA and MVD in pancreatic cancer tissues were found significantly positive correlated to each other." (PMID 27015364, 2016). "We reported that expression of FGFR2 IIIb and one of its major ligands, FGF7, correlated with venous invasion, vascular endothelial growth factor A (VEGF-A) expression, and a poor prognosis and may promote venous invasion and tumor angiogenesis in pancreatic cancers." (PMID 22701813, 2012).
endothelial dysfunction (410 papers, 2007 to 2026). In vascular diseases, endothelial dysfunction is a systemic pathological state of the endothelium (the inner lining of blood vessels) and can be broadly defined as an imbalance between vasodilating and vasoconstricting substances produced by (or acting on) the endothelium. "We found a novel pathogenic link between lncRNA H19, miR-29b, and VEGFA in hyperglycemic-induced endothelial dysfunction." (PMID 31737629, 2019). "The endothelial dysfunction and the decreased cell proliferation may cause by the deregulation of PlGF and VEGFa, generating a placental dysfunction." (PMID 36548566, 2022). "In vitro experiments revealed that blood neutrophils had significantly increased expression of LTF and VEGFA following LPS-stimulation and heme induces endothelial dysfunction." (PMID 41568397, 2026). "While VEGFA is essential for physiological angiogenesis, its pathological overexpression in diabetic conditions exacerbates endothelial dysfunction and glomerular hyperfiltration." (PMID 41323135, 2025). "Here, we found that whole body Sirt3-deficient mice exhibited reduced renal capillary density, reflecting endothelial dysfunction, and VEGFA expression compared to wild-type mice." (PMID 37816025, 2023). "VEGFA is known to be a pro-angiogenic factor that increases vascular permeability and contributes to the endothelial dysfunction that occurs in DM." (PMID 37863950, 2023). "A recent research reported that VEGFA was a latent marker of endothelial dysfunction in postmenopausal osteoporosis." (PMID 37089711, 2023). "Up-regulated VEGFA in severe COVID-19 cases is in line with the findings of the study where it has been indicated as a markers of endothelial dysfunction with significant correlation with disease severity." (PMID 34824360, 2021). "In this study, we show that H19/miR-29b/VEGFA signaling pathway plays a role in hyperglycemic-induced endothelial dysfunction." (PMID 31737629, 2019). "With our report, VEGFA rivals IL6 as the most replicated ALI genetic risk factor, and focuses attention on the critical contribution of endothelial dysfunction to the development of ALI." (PMID 22742663, 2012). "Recent research indicates that senescent macrophages in aged murine hindlimb muscle promote endothelial dysfunction by increasing the production of the anti‐angiogenic factor VEGFA‐165B (vascular endothelial growth factor), thereby impairing ischemia‐induced angiogenesis in aged murine hindlimbs." (PMID 41180381, 2025). "MiR-195-5p targets VEGFA to promote endothelial dysfunction in GDM." (PMID 40877960, 2025). "Another miRNA implicated in vascular health is miR-195-5p, which facilitates endothelial dysfunction by inhibiting vascular endothelial growth factor A. Its downregulation by pioglitazone may therefore exert protective effects with clinical relevance." (PMID 41295241, 2025). "Vascular endothelial growth factor-A concentrations have been shown to be elevated in inflammatory diseases that may be the result of endothelial dysfunction in human." (PMID 38839816, 2024). "Also, high AUC for Ang 2:Ang1, Ang 2:Tie 2, ICAM1:VCAM-1, and VEGFA: Ang 2 ratios suggest endothelial dysfunction and instability, key factors in SCD and angiogenesis." (PMID 39749215, 2024). "The changes in retrotransposon-derived enhancer activities may also play a role in endothelial dysfunction of COVID-19 patients via vascular endothelial growth factor A (VEGFA) and endoglin (ENG) gene dysregulation." (PMID 38003607, 2023). "Besides, endothelial dysfunction and vascular remodeling caused by IL-6, TGF-β, TNF-α, EGFR, and VEGFA are also some of the core features of CVD." (PMID 32454875, 2020). "Endothelial dysfunction could be characterized by the decrease in cell viability and an increase in the release of lactate dehydrogenase as well as overproduction of VEGFA." (PMID 27070575, 2016).
endothelial dysfunction (continued). "In conclusion, we successfully identified three “real” hub genes (VEGFA, CDC25A, and LOX), and six crucial miRNAs (hsa-mir-24-3p, hsa-mir-124-3p, hsa-mir-195-5p, hsa-mir-146a-5p, hsa-mir-155-5p, and hsa-mir-23b-3p) associated with endothelial dysfunction in HPH based on bioinformatic analysis." (PMID 36483920, 2022). "We identified inflammatory and endothelial dysfunction markers (ADAMTS-13, TNF-α, GDF-15, MIP-1β, VEGFA, MPO, and MIC-1) that cooperate in a common pathway and are increased in FD patients’ plasma samples." (PMID 38892211, 2024). "In the context of chronic liver disease, vascular endothelial growth factor A (VEGFA) acts as a crucial regulator of angiogenesis, contributing to endothelial dysfunction and immune cell infiltration." (PMID 39081807, 2024). "The results obtained in the present study have highlighted that endothelial dysfunction impacts bone mass through genetic participation of eNOS, ACE and VEGFA genes." (PMID 33499313, 2021). "PTPN1 is of particular interest, since it encodes PTP1B, a negative regulator of the insulin receptor signaling and the vascular endothelial growth factor A (VEGFA), contributing therefore to both insulin resistance and endothelial dysfunction." (PMID 34722683, 2021).